CD4 (CD4 molecule)
Diseases named in the same sentence as CD4 in open-access papers (continued):
Sharing a sentence is not in itself a finding about the gene and the disease.
tumor (continued). "CXCL9 is a critical chemokine that binds CXCR3 on T cells, enhancing recruitment of cytotoxic CD8+ T cells into the tumor and promoting the differentiation of inflammatory T helper type 1 (Th1) and Th17 CD4 T cells." (PMID 33508232, 2021). "In contrast, immunosuppressive CD4+ Tregs have an integral role in immune tolerance, thus actively interfering with anti-tumor responses." (PMID 33669271, 2021). "The NUP62CL regulated tumor immunology was conclusively indicated by the positive correlation with memory CD4+ T cells and the significant aspect of our study entailing the NUP62CL expression regarding the immune infiltration levels in LUAD." (PMID 33934535, 2021). "Our study suggests that CD4+ T cells infiltrating the tumor microenvironment support and encourage the activity of other immune cells by releasing T-cell cytokines." (PMID 33619320, 2021). "The KVax vaccine also increased tumor-infiltrating CD4+ T cells, decreased Tregs, and significantly increased a CD4+ effector cell subset as well as the ratio of this subset to Tregs." (PMID 34302042, 2021). "We further examined the expression of known tumor-promoting markers in these immune subpopulations, confirming that CD4_CXCL13, CD4_FOXP3, CD8_CXCL13, CD8_ISG15, Mac_C1QA, Mac_ISG15 and Mac_SPP1 cells were tumor-promoting immune cells." (PMID 35087839, 2021). "Upon deleting DC1 from the tumor microenvironment, DC2s were able to stimulate an effective CD4+ T cell–driven antitumor immune response, restoring spontaneous antitumor immunity." (PMID 34283809, 2021). "Among the high salt activated CD4+T cell treated cohorts, CD4+T cells obtained from DLNs demonstrated significantly reduced tumor growth (day 45, high salt: 97 ± 24 mm3 vs. mannitol: 292 ± 46 mm3, p < 0.05)." (PMID 33918403, 2021). "This is coupled with enhanced infiltration and activation of tumor-specific immune cells, including macrophages, neutrophils, NK cells, CD4+, and CD8+ T cells, and/or the reactivation of dysfunctional effector cells." (PMID 34829795, 2021). "CD28 are a very important co-stimulatory marker, which is required as a secondary signal for activated CD8+ T cells and CD4+ T cells exerting anti-tumor response." (PMID 34488711, 2021). "There, all the different multimodal combination treatments tested promoted the increase in the frequency of effector CD4+ T cells in the tumor lesion." (PMID 33602696, 2021). "Comparison of tumor biopsies before and after treatment reveals an increase of activated, conventional CD4+ tumor-infiltrating lymphocytes (TIL) in most patients and higher clonality by TCRβ sequencing." (PMID 33594075, 2021). "These advantages were in vitro skewing responses towards CD8+ T cells, increased efficacy at low doses, and longevity of MHC Class I peptide display; and in mouse models, a more robust humoral response, more activated CD4+ T cells, and control of tumor growth." (PMID 35095862, 2021). "This study highlighted the role of TAMs in modulating the epigenetic profile of tumor infiltrating CD4+ T cells towards a pro-tumoral phenotype." (PMID 34262562, 2021). "Tumor-derived miR-214 is reported to be transported to CD4+ T cells and promotes the expansion of Treg by downregulating the expression of PENT." (PMID 34084160, 2021). "Accordingly, various conventional CD4+ T cells are involved in antitumor or tumor-promoting processes, whereas CD4+ Treg suppresses antitumor immunity in the TME." (PMID 34663810, 2021). "In EOC, CD8+, CD4+ T-helper 1 (Th1), and natural killer (NK) cells reportedly participate in tumor suppression responses, whereas CD4+ T-helper 2 (Th2), FoxP3+ T-regulatory (Treg), and dendritic cells contribute to immunosuppression." (PMID 34071938, 2021). "Mechanistically, the stimulation via CD40 rescues CD4+ T cell helper activity, promoting the generation of tumor-specific CD8+ T cells." (PMID 33671252, 2021).
tumor (continued). "Within the tumor-infiltrating CD4+ T cell, 203 genes adjusted p value <0.05, log-fold change ≥0.5 and ∆ cell percent >10%." (PMID 33504936, 2021). "The enzyme induced apoptosis in normal CD4+ T cells, and normal fibroblast at a concentration of 20 U/mL; however, cell viability was much higher than in tumor cells." (PMID 34948436, 2021). "Some argued that cytotoxic CD4+ T cells regulated the tumor rejection in a cytolytic molecules-dependent way (e.g., perforin, granzyme B)." (PMID 34631551, 2021). "The expression level of CDH2(r = 0.263, P = 3.54 × 10−7), CDH6 (r = 0.307, P = 2.04 × 10−9) and CDH10 (r = 0.33, P = 9.99 × 10−11) in GC tumor tissues were closely related to CD4 + T cell immune infiltration." (PMID 34880371, 2021). "For the MHC-class II-negative tumor cells, CD4+ T cells can produce a vast range of cytokines that mediate inflammatory and effector immune responses; TNF and IFN-γ are the most important cytokines that are mainly produced by T helper (Th) 1 cells." (PMID 35003090, 2021). "Tumor-infiltrating CD4+ T cells showed significantly elevated expression of PD-1 (NT; 32.5 ± 2.0 vs. TT; 46.3 ± 2.7), TIM-3 (NT; 2.7 ± 0.3 vs. TT; 10.8 ± 1.3) and TIGIT (NT; 26.5 ± 1.8 vs. TT; 37.0 ± 2.1), but not LAG-3." (PMID 33477864, 2021). "In concordance with these data, we identified a population of bystander BTLA+ CD4+ T cells in proximity to tumor cells." (PMID 34885092, 2021). "CD4+ T TILs with cytotoxic capacity were shown to reject tumor cells and incorporate B TILs release of cytokines to drive cytotoxic immune responses to the tumor cells." (PMID 34089486, 2021). "The recognition that CD4+ T cells can also mediate cytotoxicity in cancer should lead to novel approaches to further enhance their direct anti-tumor activity in patients." (PMID 34910940, 2021). "CD4+T cells themselves are not the main immune subtypes of treatment, but the participation of CD4+T cells is also related to the production of effective anti-tumor response." (PMID 34307389, 2021). "Future research can optimize this immunotherapeutic strategy for eliciting tumor-specific CD4+ T cell responses by considering antigen dosing and immunogenicity, timing of the therapy, the role of adjuvants, immunosuppressive TME, and combinational strategies." (PMID 34012451, 2021). "Loading of patient autologous DC with previously identified immunogenic epitopes from tumor antigens and reinfusion of antigen-loaded DC can lead to the induction of specific anti-tumor CD4+ TH1 responses." (PMID 34012451, 2021). "The restriction of glucose supplies due to the high rates of glycolysis in tumor cells impairs the anti-tumor function of CD4+ T cells, possibly by blocking the secretion of IFN-γ." (PMID 33732706, 2021). "Batf−/− mice exhibited significantly lower numbers of tumor-infiltrating CD8+ T cells per mm3 of tumor volume as compared to wild-type controls following IL-21-producing CD4+ T cell ACT." (PMID 33809259, 2021). "The cytotoxic CD4+ T cells played important roles in anti-tumor immunity and were reported to be a close relative of Th1 cells." (PMID 33791306, 2021). "There was a trend towards a lower proportion of CD4+FoxP3+ regulatory T-cells in the tumor microenvironment of patients exposed to anti-PD-1 compared to control patients (p = 0.0571)." (PMID 34771650, 2021). "The levels of tumour-infiltrating CD4+ Tem cells, CD4+ T cells, and CD8+ Tem cells were lower in our elderly patients than in the young patients." (PMID 33436826, 2021). "CD8+ cytotoxic T lymphocytes (CTLs), usually supported by CD4+ T helper 1 (Th1) cells, are considered the major effector immune cells directed against tumor cells." (PMID 33494389, 2021). "Within the same tumor, areas with low tumor ASCL1 levels exhibited more CD8+ and CD4+ T cell infiltration, whereas areas with high tumor ASCL1 levels showed fewer CD8+ or CD4+ T cells." (PMID 33750914, 2021).
tumor (continued). "We found that the infiltrating levels of memory activated CD4+T cells were significantly lower and regulatory Tregs cells were higher in primary tumor microenvironment (PTME) with metastasis." (PMID 34249930, 2021). "Tregs can thus inhibit the anti-tumor immune response by suppressing the activity of both tumor-specific (CD8+ cytotoxic T lymphocytes and CD4+ T helper cells) and tumor unspecific effector cells (natural killer [NK] and NK T cells)." (PMID 34066606, 2021). "Similar to advanced human OCs, we found a high percentage of tumor-infiltrating Treg cells (~40% of total CD4+ TILs) in untreated (PBS) animals." (PMID 33723260, 2021). "Regarding T cells, CD8+ T cell infiltration is known to induce an anti-tumor cytotoxic response, whereas the prognostic value of CD4+ immune cell infiltration is somewhat controversial." (PMID 34228637, 2021). "CD4+ T cells have been shown to promote tumor regression via IL-2 secretion, by directly eliminating cancer cells or by augmenting tumor-specific CD8+ T cell function." (PMID 35087529, 2021). "We found that in tumor-bearing Pik3cg−/− mice, PD-1 expression was significantly higher in both CD4+ and CD8+ cells of the lymph nodes and spleens, though we did not observe this difference in the tumor microenvironment." (PMID 33668795, 2021). "In this review, we describe how different CD4 T cell subsets can contribute to tumor immune responses during immunotherapy." (PMID 34064410, 2021). "We tested CD45+, CD3+, CD4+, CD8+, and Foxp3+ immune markers in both the tumor core area and tumor-associated stroma." (PMID 33580130, 2021). "Fresh tumor tissues were harvested 14 and 21 days after inoculation in BALB/c mice, respectively, then single-cell suspension was prepared and stained for tumor-infiltrating CD4+, CD8+ T lymphocytes, and CD11b+CD11c+." (PMID 35693216, 2021). "In the tumor microenvironment (TME), lineage commitments of CD4+ T cells reflect initiation of new programs of gene expression within tumor infiltrating naïve T cells." (PMID 34012510, 2021). "Among them, the cells with the highest amount in tumor tissues are M2 macrophages, M0 macrophages, M1 macrophages, CD4+ resting T cells and resting mast cells, which were all significantly more than those in normal tissue." (PMID 34805160, 2021). "TNF was also involved in de novo expression of MHC class II in melanomas, which results in favoring the accumulation of tumor-specific CD4+ T cells in the tumor microenvironment and local immune response." (PMID 34068679, 2021). "As for tumor immune infiltration, NOP2 was significantly associated with CD4 + T cells, B cells, neutrophils cells, CD8 + T cells and dendritic cell infiltration (all P < 0.001)." (PMID 34334108, 2021). "Their high frequency among CD4+ T cells within tumor-infiltrating lymphocytes (TILs) or a high ratio of FOXP3+ Tregs to CD8+ T cells is associated with a poor prognosis in the majority of solid tumors (for review." (PMID 33924428, 2021). "The immune cell populations such as T cells CD4 memory resting and NK cell resting have higher scores in normal group, and T cells CD4 memory activated and Mast cells activated have higher scores in tumor cells related to OS." (PMID 34922489, 2021). "Overall, with reference to LUAD, we analyzed 22 immune cell subsets and ascertained NUP62CL significantly correlated with tumor‐infiltrating memory CD4+ T cells and tumor infiltrating B lymphocytes, primarily as potential prognostic biomarkers for progression." (PMID 33934535, 2021). "Here, we review current status of these immunotherapeutic approaches to stimulate tumor specific CD4+ T cell responses, focusing on peptide vaccines, adoptive T cell transfer and chimeric antigen receptor T cell therapy." (PMID 34012451, 2021).
tumor (continued). "A key unanswered question is the relative contribution of cytotoxic CD4+ T cells in vivo for either immunosurveillance against tumor progression, or response to immunotherapy, set against the functional contributions of other immune effector populations." (PMID 34910940, 2021). "We further showed that transfecting CIITA into tumor cells raised their ability to in vivo prime naïve CD4+ cells, thus, they serve as APCs." (PMID 33592498, 2021). "Our data showed infiltration of T (CD3+), CD8 T (CD8+) and B cells (CD20+) in more than 50% of the tumor samples and a lower infiltration of CD4 T cells (CD4+) and CL (TIA1+)." (PMID 34885185, 2021). "The third subtype of T cells involved in anti-tumor responses after PDT are a unique subpopulation in the CD4+ category which are regulatory or suppressive in nature; they are also referred to as suppressor T cells, or Tregs." (PMID 34068491, 2021). "(K–L) Tumor of the mouse models from (F) were evaluated for infiltration of both CD4+ and CD8+ T cells on day 16 post implantation, which were higher in 6PGD blocked mice, as shown by representative flowgram (K) and bar graphs (L)." (PMID 34709178, 2021). "Relative abundance of DCs, macrophages, and CD4+ T-cells, as well as tumor stage, HPV16 E7 DNA CN, and E7 mRNA levels, were selected as variables." (PMID 34771506, 2021). "Meanwhile, blocking CD36 on DCs with monoclonal antibodies recused their antigen presentation ability by MHC class II molecules, which improved CD4+ T cell priming and consequently boosted anti-tumor immune response." (PMID 34742349, 2021). "Experiments in vivo showed that fecal microbiota transplantation using respondent feces promoted the aggregation of CXCR3+CD4+ T cells into tumor tissues and improved the antitumor activity of PD‐1 blockade." (PMID 34382349, 2021). "IFNγ strongly promotes inflammatory responses and has been shown to augment the function of tumor-infiltrating immune cells including CD4+ TH1 cells, CD8+ T cells, dendritic cells and macrophages, while suppressing TH2 cells and Tregs." (PMID 33842331, 2021). "This is in accordance with the demonstration that PD-1 enhances regulatory properties in Treg cells and inhibition of anti-tumor activity of CD4 Teff cells in MM, indicating a role of PD-1 in the MM clinical outcome." (PMID 34502204, 2021). "Dynamic PET imaging studies using 23 were performed in mice bearing U87·CD4 or U87·CD4·CXCR4 tumor cells." (PMID 34500609, 2021). "Whereas, initial studies were focused on the role of CD8+ T cells in mediating anti-tumor immunity, subsequent work established that the immunogenic mutanome—against former expectations- predominantly induced a CD4+ T cell response in mice and humans." (PMID 35097027, 2021). "PSGL-1 deficient (Selplg−/−) mice were shown to have enhanced anti-viral and anti-tumor immunity, with T cells escaping functional exhaustion partly due to their enhanced CD4+ T cell responses." (PMID 33708224, 2021). "The percentage of CD4+CD25+FoxP3+ Tregs among the total tumor-infiltrated CD4+ cells is 44.45 ± 9.03 in control group as compared to 6.47 ± 1.18 in NIR treated group (P < 0.005; Student’s t-test)." (PMID 33986437, 2021). "LILRB4−/− genotype or LILRB4 blockade increased tumor immune infiltrates and the effector (Teff) to regulatory (Treg) T cell ratio and modulated phenotypes of TAMs toward less suppressive, CD4+ T cells to Th1 effector, and CD8+ T cells to less exhausted." (PMID 33974041, 2021). "Exhausted CD8+ T cells and regulatory CD4+ T cells (CD4+ Tregs) were enriched in OSCC tumors, potentially linked to tumor immunosuppression." (PMID 33513276, 2021). "In this review, we described the epigenetic factors that govern CD4+ T cells differentiation and recruitment in the tumor microenvironment and their subsequent involvement in the antitumor immunity." (PMID 34262562, 2021).
tumor (continued). "IHC analysis demonstrated that the proportions of tumor-infiltrating CD4+ T cells were higher in the low-ATGPI group that in the high-ATGPI group." (PMID 34616731, 2021). "These CAF-educated DCs promoted tumor infiltration of immunosuppressive Tregs (CD4+CD25+Foxp3+) cells and decreased production of IFN-γ from CD8+ T cells." (PMID 34177901, 2021). "T cells are a very heterogeneous population: on one hand, CD8+, CD4+, and γδT cells are directly involved in the specific killing of tumor cells, directed by the recognition of tumor antigens." (PMID 33804027, 2021). "In other words, PGE2 serves as an immunosuppressor contributing to the induction of CD4+ Th2 cells and the pro-tumor efficacy of TILs." (PMID 34497832, 2021). "Adoptive transfer of tumor specific CD4+ lymphocytes has proved its efficacy in the treatment of cancer." (PMID 34262562, 2021). "Another study indicated that after PLX3397 treatment in mice with breast cancer, there was a significant depletion of macrophages in tumor tissues accompanied by an increase in the ratio of CD8+/CD4+ T cells and significantly reduced tumor growth." (PMID 34178692, 2021). "Mechanistically, ITK is required for TCR signaling and CXCR4 signaling, and thus critical for malignant T cell proliferation, differentiation and migration, while preventing anti-tumor immune responses by inhibiting TH1 CD4 T cell differentiation." (PMID 34778053, 2021). "Immune cells in HCC tissues contained dendritic cells, B cells, monocytes, CD4+ T cells, natural killer cells (NKs), CD8+ T cells, neutrophils, M1 macrophages, M2 macrophages, and tumor-associated macrophages (TAMs)." (PMID 33767990, 2021). "Previous studies showed that DC2 cells can be at least as effective as DC1 cells in the induction of anti-tumor immune responses after vaccination, and can generate anti-tumor CD4+ and CD8+ memory T cells." (PMID 34777358, 2021). "While EE was still responsible for tumor growth after CD4+ T cell and NK cell depletion, CD8+ T cells depletion abolished the antitumor effect of EE on Hepa1-6, H22 LPC-H12, and DEN + CCl4 tumor models." (PMID 34593796, 2021). "Consistently, immunofluorescence staining of tumor frozen section also validated the increased infiltration of CD4+ and CD8+ T lymphocytes." (PMID 35693216, 2021). "PDAC is described as a “cold” tumour in which an imbalance between immunosuppressive populations of CD4+ T-cells and cytotoxic CD8+ exists." (PMID 33546207, 2021). "CD4+LAIR2+ cells highly expressed Treg cell lineage markers, including IL2RA, CTLA4, TNFRSF18, ICOS, TIGIT, and tumor-associated Treg cell marker CCR8, consistent with CD4+ LAIR2+ cells being of Treg lineage and not recently activated T cells." (PMID 35008369, 2021). "Considering that IL-13 and IL-4 are primarily derived from lymphocytes, especially Th2 cells, we monitored the Th2 cell population in the lungs of MMTV-PyMT mice and detected increased infiltration of CD4+ T cells and Th2 cells along with tumor progression." (PMID 34707103, 2021). "We also found that B cell related proteins (CD20, BAD, BCL-2, CD27, BIM) were most highly expressed in the stromal compartments while expression of lymphocyte-related markers (CD3, CD8, CD4, Tim-3) were elevated in tumor compartments." (PMID 34838031, 2021). "CD8 cytotoxic T cells and CD4 Th1 cells are the most important contributors to the adaptive immune cellular host defence against tumours." (PMID 34885119, 2021). "This in turn causes the transfer of a large amount of CXCR3+CD8+T and CXCR3+CD4+T cells into the tumors, which take part in anti-tumor activities." (PMID 35095920, 2021). "The exhaustion markers PD-1, LAG-3, and TIM-3 were not differentially upregulated over 13 days on BM or splenic localized CD4+ and CD8+ CXCR5 CAR-T compared to SP6 CAR-T cells, thus exhaustion seems to be unlikely involved in loss of tumor control." (PMID 33431832, 2021).